LYZ (lysozyme)
Diseases named in the same sentence as LYZ in open-access papers (continued):
Sharing a sentence is not in itself a finding about the gene and the disease.
Arthritis (4 papers, 2017 to 2021). Inflammation of a joint. "After 7 days, they induced an experimental immune-complex mediated arthritis by injecting the cationic antigen lysozyme coupled to poly-L-lysine (PLL) in knee joints of mice that were previously treated with polyclonal antibodies directed against lysozyme." (PMID 33799992, 2021). "Mice injected intravenously with heat-inactivated polyclonal rabbit anti-lysozyme serum, followed by an injection with poly-L-lysine-coupled lysozyme in the joint developed arthritis." (PMID 29495570, 2018). "In addition, the authors induced an experimental arthritis by injecting hen egg lysozyme coupled to poly-L-lysine into the knee joints of mice that previously had received polyclonal antibodies directed against lysozyme." (PMID 33799992, 2021). "We show that intact caspase-8 signaling maintains opposing roles in lysozyme-M- and CD11c-expressing cells in the joint; namely, caspase-8 is crucial in CD11c-expressing cells to delay arthritis induction, while caspase-8 in lysozyme M-expressing cells hinders arthritis resolution." (PMID 28978351, 2017).
chronic myelomonocytic leukemia (4 papers, 2022 to 2025). A myelodysplastic/myeloproliferative neoplasm which is characterized by persistent monocytosis, absence of a Philadelphia chromosome and BCR/ABL fusion gene, fewer than 20 percent blasts in the bone marrow and blood, myelodysplasia, and absence of PDGFRA or PDGFRB rearrangement. "Lysozymuria is a rare paraneoplastic complication of AML and chronic myelomonocytic leukemia characterized by lysozyme." (PMID 36051078, 2022).
depression (4 papers, 2019 to 2022). "The following are promising salivary biomarkers of stress, anxiety or depression: cortisol, immunoglobulin A (sIgA), lysozyme, melatonin, α-amylase (sAA), chromogranin A (CgA) and fibroblast growth factor 2 (FGF-2)." (PMID 33535653, 2021). "Results obtained from these salivary biomarkers offer insight into individuals’ stress levels, anxiety or depression, primarily using salivary cortisol, immunoglobulin A (sIgA), salivary alpha-amylase, chromogranin A, lysozyme, melatonin, and fibroblast growth factor 2 (FGF-2)." (PMID 36285968, 2022). "In the literature, you can find publications indicating the relationship between stress, depression and/or anxiety and the concentration of cortisol, immunoglobulin A, lysozyme, melatonin, alpha-amylase, chromogranin A and/or fibroblast growth factor 2 in saliva." (PMID 33535653, 2021). "However, there is no information on the concentration of lysozyme in the saliva of people suffering from depression or anxiety." (PMID 33535653, 2021).
diabetic nephropathy (4 papers, 2020 to 2025). "LYZ is markedly expressed in ovarian and estrogen-related immune responses and prominent in the immune invasion of diseases such as diabetic nephropathy and thyroid cancer 29-32." (PMID 39991571, 2025). "Patients suffering from diabetic nephropathy can also show increased urinary lysozyme levels, up to 10 μg/mL." (PMID 33804443, 2021).
Granuloma (4 papers, 2023 to 2025). A compact, organized collection of mature mononuclear phagocytes, which may be but is not necessarily accompanied by accessory features such as necrosis. "In multivariate analysis, only weight loss, necrotic granuloma, normal serum lysozyme level and polyclonal hypergammaglobulinemia remained significantly associated with TB." (PMID 38787250, 2024). "The multivariate analysis showed that weight loss, necrotic granuloma, normal serum lysozyme level and hypergammaglobulinemia were significantly associated with TB." (PMID 38787250, 2024). "Following multivariate analysis, only weight loss, necrotic granuloma, normal serum lysozyme level and hypergammaglobulinemia remained significantly associated with TB." (PMID 38787250, 2024). "We found in multivariate analysis that weight loss, necrotic granuloma, non-elevated lysozyme and hypergammaglobulinemia remained significantly associated with TB." (PMID 38787250, 2024).
Hepatitis (4 papers, 2021 to 2025). Inflammation of the liver. "The main components of CM, such as lysozyme, Lf and lactoperoxidase are important in the treatment of some inflammatory diseases, including hepatitis, allergies, lactose intolerance and liver damage caused by alcohol in some parts of the world." (PMID 35493477, 2022). "She had an unremarkable workup including a complete cell blood count, comprehensive metabolic panel, urine analysis, QuantiFERON Tb gold, hepatitis panel, angiotensin-converting enzyme, lysozyme, and a chest X-ray." (PMID 41194826, 2025). "Lab studies, including complete cell blood count, comprehensive metabolic panel, urine analysis, QuantiFERON Tb gold, hepatitis panel, angiotensin-converting enzyme, and lysozyme, were all within normal limits." (PMID 41194826, 2025). "More studies showed that lysozyme was anti-adenovirus and can be used to treat herpes, mumps, chickenpox, hepatitis, influenza, and atypical pneumonia." (PMID 34925025, 2021). "For example, it has been reported that the lysozyme chloride at the dose of 60–170 mg for 4–24 weeks reduced the incidence of hepatitis after transfusion from 20 to 8%." (PMID 34925025, 2021).
Hypercalcemia (4 papers, 2007 to 2024). An abnormally increased calcium concentration in the blood. "Due to the presence of hypercalcemia and increased lysozyme level, we also performed 1-α hydroxylase (CYP27B1) and lysozyme staining." (PMID 38890580, 2024). "The laboratory tests showed isolated lymphopenia, slight hypercalcemia, normal serum protein electrophoresis, and elevated ACE and lysozyme." (PMID 36672683, 2023). "Finally it was only the synopsis of the clinical manifestations, the pathologic lab tests (hypercalcemia, ACE, IL-2-Receptor, lysozyme) and finally the response to treatment with steroids which allowed to confirm the diagnosis." (PMID 18053167, 2007).
metabolic syndrome (4 papers, 2013 to 2021). A cluster of metabolic risk factors for CARDIOVASCULAR DISEASES and TYPE 2 DIABETES MELLITUS. "And, in obese subjects with hyperinsulinemia and dyslipidemia, the translocation of peptidoglycan was linked to plasma lysozyme, which was negatively correlated with HOMA-IR, HbA1c, and cholesterol." (PMID 33815293, 2021).
monocytic leukemia (4 papers, 1987 to 2022). "The control of lysozyme levels allows to differentiate acute myelogenous or monocytic leukemia from acute lymphatic leukemia and to monitor the response to the treatments of these pathologies in sick patients." (PMID 33374794, 2020). "Changes in lysozyme levels can indicate pathological conditions; for example, monitoring lysozyme levels allows differentiation between acute myelogenous or monocyte leukaemia and acute lymphatic leukaemia, and a tracking response to treatments in cancer patients." (PMID 35049673, 2022). "Among them, HS and monocytic leukemia have some similarities in their IHC phenotypes, as both can express one or more monocytic neoplasm antigens, such as CD68, CD163 and lysozyme." (PMID 26187047, 2015). "Ninety-seven cases of chronic myelomonocytic leukaemia (CMML) were examined retrospectively for survival and possible prognostic factors including age, total white cell count, peripheral blood and bone marrow monocyte counts, % double esterase (DE) positive cells in bone marrow and serum lysozyme." (PMID 3476144, 1987).
Renal amyloidosis (4 papers, 2009 to 2025). A form of amyloidosis that affects the kidney. "The sequence of the cloned EWL gene was identical to the sequence reported in the Gallus lysozyme (renal amyloidosis)." (PMID 40283196, 2025). "Expression levels of the lysozyme (renal amyloidosis) gene (LYZ) did not change significantly in PBMC from the Boran over time, although they did tend to decrease over time." (PMID 19409086, 2009).
sicca syndrome (4 papers, 2014 to 2025). "These upper gastrointestinal tract symptoms have already been reported in most of patients with ALys and are probably related, as sicca syndrome, to the local production and deposit of the abnormal lysozyme protein." (PMID 25217048, 2014). "It was found that lysozyme was decreased in idiopathic dry eye and Sjogren syndrome compared to controls." (PMID 26605353, 2014). "In a large study with 262 patients (78 patients with Sjogren syndrome), the concentrations of the lysozyme and lactoferrin protein in tear samples in Sjogren syndrome were determined." (PMID 26605353, 2014). "To this end, we evaluated theconcentration of tear lysozyme in individuals with Sjögren’s syndrome (SS),meibomian gland dysfunction (MGD), and non-dry-eye disease (NDED)." (PMID 34431892, 2021).
syphilis (4 papers, 2016 to 2025). A contagious bacterial infection caused by the spirochete Treponema pallidum. "Serologic testing for HIV, syphilis, herpes viruses, and toxoplasmosis as well as the serum angiotensin converting enzyme and lysozyme levels were also ordered." (PMID 30076485, 2018).
ulcerative colitis (4 papers, 2014 to 2025). An inflammatory bowel disease involving the mucosal surface of the large intestine and rectum. "Previously, we found that BBR can alleviate the damage of DSS-induced ulcerative colitis and reduce the secretion of lysozyme." (PMID 35893243, 2022). "In ulcerative colitis in remission, lysozyme is up-regulated in metaplastic Paneth cells (left colon)." (PMID 25437608, 2014). "In active ulcerative colitis, lysozyme is up-regulated in metaplastic Paneth cells (left colon) and in the deep half of the crypts." (PMID 25437608, 2014).
upper respiratory tract infection (4 papers, 2021 to 2024). "The usefulness of lysozyme in upper respiratory tract infections was reported in a review analyzing the antimicrobial peptides present in respiratory secretions and reporting how lysozyme can combine antimicrobial activities with antiviral activities." (PMID 38338396, 2024). "While lysozyme has not previously been measured in tears in relation to trachoma, a fall in levels has previously been observed in upper respiratory tract infections and dry eye disorders." (PMID 37862368, 2023).
acute kidney injury (3 papers, 2023 to 2025). Sudden and sustained deterioration of the kidney function characterized by decreased glomerular filtration rate, increased serum creatinine or oliguria. "In spite of all these findings in almost 60 years and a huge gap since the 90’s, lysozyme seems to have been forgotten as potential early biomarker in acute kidney injury." (PMID 37751458, 2023). "Alterations in urine and serum levels of lysozyme were detected in acute renal failure." (PMID 37751458, 2023). "The toxic buildup of lysozyme can damage renal tubules, leading to acute kidney injury (AKI) or progression to chronic kidney disease (CKD)." (PMID 41181405, 2025).
Allergy (3 papers, 2016 to 2022). An allergy is an immune response or reaction to substances that are usually not harmful. "The lack of breast milk feeding during the first six months, an important source of secretory IgA, lysozyme and lactotransferrin, increases the risk of infections including respiratory infections as well as the risk of allergy." (PMID 27642394, 2016).
alopecia (3 papers, 2013 to 2025). Hair loss usually from the scalp. "LYZ-Ndufs4 showed a similar phenotype and disease conditions with significant attenuation of the alopecia." (PMID 30993080, 2019). "In women, a significant (P < 0.001) increase in lysozyme deposits on elastotic fibres was the most prominent effect, correlating with alopecia." (PMID 24455724, 2013). "In addition to preserving salivary flow and lysozyme output, NACA conferred protection against radiation-induced alopecia, suggesting a potential role as a systemic ROS scavenger." (PMID 40940999, 2025).
autism (3 papers, 2011 to 2024). Persistent deficits in social interaction and communication and interaction as well as a markedly restricted repertoire of activity and interest as well as repetitive patterns of behavior. "Lysozyme were lower in the autism group compared to controls, and the lower levels of lyszoymes were associated with probiotic usage; it is possible that probiotics decrease the need for lysozyme to be excreted to defend against pathogenic bacteria." (PMID 21410934, 2011). "In this study, lysozyme levels were lower in children with autism (-28%, p = 0.04); this difference was significant for the A-Probiotic group, but not for the A-No-Probiotic group." (PMID 21410934, 2011). "Secretory IgA was highly correlated with lysozyme for the autism group (R = 0.69, p < 0.001), and moderately correlated for the controls (R = 0.35, p < 0.01)." (PMID 21410934, 2011). "The autism group had a lower level of lysozyme (-27%, p = 0.03 by Wilcox analysis), but no other significant differences." (PMID 21410934, 2011).
bacteremia (3 papers, 2018 to 2020). "Nevertheless, the activity empowerment was quite variable: in the case of lysozyme + colistin, the ranges of fold-reduction in viability were 5.8–821.3 for bacteremia, and 6.9–145.5 for CF isolates." (PMID 30837659, 2019). "It has previously been shown that genes involved in the biosynthesis and maintenance of LPS and peptidoglycan contribute to the fitness of A. baumannii during bacteremia, and that both LPS and peptidoglycan contribute to bacterial cell stability and resistance to lysozyme in the host environment." (PMID 33207684, 2020).
cervical cancer (3 papers, 2016 to 2025). A primary or metastatic malignant neoplasm involving the cervix. "Cox regression analysis identified 35 genes independently associated with the prognosis of cervical cancer, of which SPP1, LYZ, and MCM5 were significantly regulated in both RA and cervical cancer." (PMID 41384115, 2025). "Even though our study showed that SPP1, LYZ, and MCM5 have good clinical value and diagnostic performance in patients with cervical cancer and RA, there are still certain limitations." (PMID 41384115, 2025). "The results showed that SPP1, LYZ, and MCM5 not only had high diagnostic potential in patients with RA and cervical cancer but also showed specific binding sites with HPV 16 E6/E7 proteins through molecular docking simulation." (PMID 41384115, 2025). "Future studies should focus on collecting patients with RA and cervical cancer for high throughput sequencing to further reveal the role of SPP1, LYZ, and MCM5 in the disease." (PMID 41384115, 2025). "Immunohistochemistry results further verified the high expression of SPP1, LYZ, and MCM5 in patients with RA combined with cervical cancer." (PMID 41384115, 2025). "The findings showed that cervical cancer tissues had increased expression levels of SPP1 (p = 0.047), LYZ (p = 0.034), and MCM5 (p = 0.002) in comparison to the healthy control group; this difference was statistically significant." (PMID 41384115, 2025). "On this basis, we successfully identified three hub genes (SPP1, LYZ, and MCM5) that were differentially expressed in the prognosis of RA and cervical cancer." (PMID 41384115, 2025). "Compared with cervical cancer patients, SPP1 (p = 0.005), LYZ (p = 0.005) and MCM5 (p = 0.006) were also highly expressed in RA combined with cervical cancer, and the difference was statistically significant." (PMID 41384115, 2025). "This study successfully identified SPP1, LYZ, and MCM5 as key hub genes for the comorbidity of RA and cervical cancer." (PMID 41384115, 2025). "Western blot analysis confirmed that LYZ, ORM1, LYN, STMN1 significantly increased in cervical cancer, while LUM, BGN, KRT4 significantly decreased." (PMID 27690342, 2016). "Furthermore, we explored the molecular mechanism of comorbidity between RA and cervical cancer by immunohistochemistry analysis of patients with cervical cancer combined with RA, and successfully identified three key hub genes: SPP1, LYZ, and MCM5." (PMID 41384115, 2025). "Next, we evaluated the three genes’ potential for diagnosis, SPP1, LYZ, and MCM5, in the RA test set data (GSE55235, GSE55457, and GSE77298) and validation set (GSE89408) as well as the cervical cancer test data sets (TCGA and GTEx) and validation set (GSE63514)." (PMID 41384115, 2025). "We found that LYZ, ORM1, LYN and STMN1 significantly increased in cervical cancer samples." (PMID 27690342, 2016).
chronic kidney disease (3 papers, 2023 to 2025). Impairment of the renal function secondary to chronic kidney damage persisting for three or more months. "In case of chronic kidney disease (CKD), lysozyme was measured among other CKD-associated plasma proteins in a multiple reaction monitoring (MRM) mass spectrometry (MS) assay in order to determine their association with kidney function and disease outcome." (PMID 37751458, 2023). "LYZ may be a promising therapeutic target for chronic kidney disease." (PMID 36814902, 2023).
co-infection (3 papers, 2018 to 2022). "Interestingly, turmeric oil significantly enhances HSP70, HSP90, lysozyme, and IgM level in P. hypophthalmus fingerlings against I. multifiliis and A. hydrophila co-infection." (PMID 36119096, 2022). "The level of total protein, gamma globulins, the activity of lysozyme and ceruloplasmin, as well as the metabolic activity and potential killing activity of phagocytes were measured: 0, 24 h, 72 h, 7 days, 14 days, and 21 days after co-infection." (PMID 34359116, 2021).
gastric cancer (3 papers, 2011 to 2021). A primary or metastatic malignant neoplasm involving the stomach. "It is found that the increased expression of lysozyme in gastric cancer is related to the poor prognosis of patients." (PMID 34925025, 2021). "The 2-years poor survival rate of gastric cancer patients implied the poor prognosis of advanced gastric cancer containing lysozyme." (PMID 34925025, 2021). "Also, about 1/3 of gastric carcinomas have been shown to exhibit immunoreactivity for lysozyme components, supported by ultrastructural (electron microscopic) findings, which has been described as abortive expression of Paneth cell differentiation." (PMID 33859932, 2021). "We also discovered long-range epigenetic silencing (LRES) regions in gastric cancer tissue and identified several hypermethylated genes (MDM2, DYRK2, and LYZ) within these regions." (PMID 22133303, 2011).
glaucoma (3 papers, 2016 to 2022). Increased pressure in the eyeball due to obstruction of the outflow of aqueous humor. "Lysozyme (LYZ) and S100A6 protein expressions have been linked to dry eye disease and glaucoma drug adverse effects; LYZ expression decreases while S100A6 increases in response to these conditions." (PMID 30069167, 2018). "A new drug delivery system consisting of NDembedded in contact lens (for drug sequestration and sustained release) was tested using timolol maleate (drug used for treating ocular disease, glaucoma) in the presence of lysozyme in trabecular meshwork cells." (PMID 28959329, 2016).
herpes simplex (3 papers, 2021 to 2025). "The indirect evidence for the role of lysozyme in combating viruses comes from the observation that ocular herpes simplex infections were associated with a decrease in lysozyme levels in the infected eye compared to the healthy eye of the same patient and in general to the eyes of healthy people." (PMID 38338396, 2024). "Although lysozyme’s antiviral properties are less well understood, research dating back to the late 1950s reported its efficacy against herpes simplex, herpes zoster, warts, condylomata acuminata, aphthosis, and vaccinia viruses." (PMID 41306594, 2025).
hyperlipidemia (3 papers, 2021 to 2024). "Analyte-independent interference is typically caused by lipemia, whereas analyte-dependent interference is attributed to various causes, including heterophilic antibodies, human antianimal antibodies, complement, lysozyme, and paraprotein." (PMID 34745256, 2021).